LAMC2 (laminin subunit gamma 2)
Diseases named in the same sentence as LAMC2 in open-access papers (continued):
Sharing a sentence is not in itself a finding about the gene and the disease.
LAMC2 also shares sentences with these, for which no sentence is quoted: cyst (2 papers); recessive dystrophic epidermolysis bullosa (2); skin disorder (2); adenocarcinomas of the colon (1); alcoholic hepatitis (1); amelogenesis imperfecta (1); amoebiasis (1); anaplastic breast carcinoma (1); carcinomas of the pancreas (1); cervical intraepithelial neoplasia (1); clear-cell renal cell cancer (1); colorectal tumors (1); Congenital muscular dystrophy type 1A (1); COVID-19 (1); cutaneous squamous cell carcinoma (1); dental caries (1); diabetic kidney disease (1); gastric tumor (1); Herlitz Type Junctional Epidermolysis Bullosa (1); ichthyosis (1); lung disease (1); lung squamous cell carcinoma (1); metastatic melanoma (1); metastatic tumors (1); myocarditis (1); osteosarcoma (1); pancreatitis (1); Papillary thyroid carcinoma (1); penile squamous cell carcinoma (1); polycystic kidney disease (1).
A further 6 diseases each share a sentence with LAMC2 in 1 paper.